NOTCH2NLR (notch 2 N-terminal like R)
Synonyms: NOTCH2NLD
Gene: Protein-coding gene on chromosome 1 (120,723,912 to 120,794,851, forward strand). Ensembl gene ENSG00000286106.
Pathways (Reactome):
Signal Transduction: Expression of NOTCH2NL genes
Gene Ontology:
Molecular function: calcium ion binding
Biological process: animal organ development; positive regulation of signal transduction; system development
Cellular component: extracellular region
Genetic constraint (gnomAD): Loss-of-function variants: 19 observed, 13.2 expected, observed/expected ratio (o/e) 1.44, 90% interval 0.99 to 1.9. The upper end of that interval is the gene's LOEUF score, 1.9, which puts it in group 6 of 6, group 1 being the genes least tolerant of losing a copy. Missense variants: 191 observed, 192 expected, observed/expected ratio (o/e) 0.99, 90% interval 0.88 to 1.12. Synonymous variants: 82 observed, 71.68 expected, observed/expected ratio (o/e) 1.14, 90% interval 0.96 to 1.38.
Homologues: Orthologues: Drosophila melanogaster N (41% identical), Caenorhabditis elegans lin-12 (8% identical), zebrafish notchl (1% identical). Paralogues in human: NOTCH2 (92% identical), NOTCH2NLC (84% identical), NOTCH2NLB (81% identical), NOTCH2NLA (78% identical), NOTCH1 (43% identical), NOTCH3 (36% identical), SNED1 (12% identical).